TNF (tumor necrosis factor)
Diseases named in the same sentence as TNF in open-access papers (continued):
Sharing a sentence is not in itself a finding about the gene and the disease.
sarcoidosis (continued). "Interestingly, monocytes of sarcoidosis patients show an enhanced ability to aggregate in vitro after stimulation with TNF-α and interferon-β, an observation that places TNF in an ambiguous position between one of the factors contributing to the formation of the granuloma or a therapeutic target." (PMID 32823753, 2020). "Finally, evaluation of spot perturbation profiles in sarcoidosis showed upregulation of the other three spots (T, V, and X); however, none of those spots were specifically linked to TNF-alpha mediated immune/inflammatory response." (PMID 31842375, 2019). "Although the mechanism responsible for the development of sarcoidosis during anti-TNF-α therapy is not well understood, the simultaneous development of sarcoidosis and cutaneous vasculitis in the present case may suggest an underlying pathogenesis for the paradoxical inflammations." (PMID 26864464, 2016). "The mechanism by which anti-TNF agents could induce sarcoidosis remains unclear." (PMID 23983404, 2013). "Indeed, enhanced TNFα secretion by BAL macro-phages is observed in sarcoidosis." (PMID 22513006, 2012). "Therefore blockade of TNF-α should have a therapeutic effect on sarcoidosis." (PMID 23320239, 2012). "Therefore TNF is an attractive target for immunotherapy in sarcoidosis." (PMID 23039818, 2012). "The development of cutaneous sarcoidosis after TNF-blockers therapy may probably be triggered by an initial exposure to a skin antigen and it has been suggested that Propionibacterium acnes may promote the skin immune response observed in sarcoidosis." (PMID 21603192, 2011). "The usual observed standard treatment for sarcoidosis includes steroids with MTX and AZA as first line steroid-sparing agents; anti-TNF inhibitors are used for patients with contraindications to these treatments or with severe or refractory disease." (PMID 41030256, 2025). "The pathophysiology of sarcoidosis involves activation of macrophages and CD4+ T lymphocytes, leading to increased production of tumor necrosis factor-alpha (TNF-α), interleukin-2 (IL-2), interferon-gamma (IFN-γ), and serum amyloid A protein." (PMID 40988789, 2025). "Sarcoidosis patients often exhibit heightened immune responses to mycobacterial antigens such as early secreted antigenic target-6, with elevated IFN-γ and TNF-α levels indicating Th1 polarization." (PMID 40837573, 2025). "Sarcoidosis can be triggered by treatments such as ICIs, BRAF/MEK inhibitors, and tumor necrosis factor-alpha (TNF-α) blockers." (PMID 39717410, 2024). "ABCC11 is a gene that influences macrophage differentiation and induces TNF-α and IL17 through TLR4 signaling; these results as well as the novel findings above support the importance of innate immune response genes in sarcoidosis." (PMID 39080656, 2024). "As an example, BALF-EVs increase interleukins IL-1β and IL-6, Tumor Necrosis Factor α (TNFα), and CC motif chemokine Ligand 2 (CCL2) in sarcoidosis disease and acute respiratory distress syndrome (ARDS)." (PMID 36768664, 2023). "Regulation of the immune response, as well as prevention of fibrosis due to suppression of the overactive macrophages, T-cells and cytokine (TNF-a, IL-1, IFN-γ and IL−6) production can be the main approaches of the sarcoidosis treatment." (PMID 36148463, 2022). "Phenotype identification has the potential to guide therapy as has been previously shown in successful treatment of patients with sarcoidosis and CD4+ T-cell lymphopenia with the TNF-α antagonist, infliximab." (PMID 33718397, 2021). "Others also reported that BALF-derived EVs from sarcoidosis patients stimulated monocytes to release IL-1β, IL-6, CCL2, and Tumor Necrosis Factor (TNF)." (PMID 33430301, 2021). "Broncho-alveolar lavage fluid of sarcoidosis patients showed increased levels of exosomes inducing various pro-inflammatory cytokines, such as IL-1β, IL-6, and TNF (Tumor Necrosis Factor) alpha." (PMID 34440765, 2021).
sarcoidosis (continued). "In the context of sarcoidosis these results provide new puzzle pieces of the largely unknown pathogenesis of this disease suggesting a role of IL-26 in the activation of moDCs via TLR2 followed by the secretion of TNF-α, an important pathological player and therapeutical target in sarcoidosis." (PMID 33057074, 2020). "Bronchoalveolar lavage (BAL) cells from sarcoidosis patients produce more TNF-α and IL-6 in response to TLR2 agonists than healthy controls, while PBMCs from sarcoidosis patients had impaired TLR2 responses." (PMID 32256501, 2020). "We observed significantly increased IFN-γ and TNF-α secretion from Kv-stimulated PBMCs of sarcoidosis patients vs. PBMCs from healthy volunteers (IFN-γ: 207.2 pg/mL vs. 3.86 pg/mL, p = 0.0018; TNF-α: 2375 pg/mL vs. 42.82 pg/mL, p = 0.0003)." (PMID 28114394, 2017). "Despite studies showing that anti–tumor necrosis factor-α (TNF-α) treatment can successfully be used in refractory sarcoidosis, there are some case reports regarding the development of sarcoidosis with these agents." (PMID 26425632, 2015). "TNFα, PAI-1, and IGF-1 levels in EBC were closely positively correlated with BALF samples from sarcoidosis patients." (PMID 26464848, 2013). "Taken together, this meta-analysis extended previous findings on the association between the TNF-α and TNF-β genetic polymorphisms and sarcoidosis, by showing that the TNF-β gene A252G polymorphism might be a potential risk factor for the development of sarcoidosis." (PMID 24244632, 2013). "For practical reasons, we hope that this study will not remain just another endpoint of research instead of a beginning to establish the background data for further investigation on mechanisms of the TNF-α and TNF-β genes in sarcoidosis." (PMID 24244632, 2013). "This suppression correlated with high content of TNF-α and IL-1 in sarcoidosis patients stage II-III (7.7 ± 2.9 ng/ml TNF-α and 157 ± 53 U/ml IL-1 compared to 3.4 ± 2.4 ng/ml TNF-α and 43 U/ml IL-1 in controls; p < 0.01 and p < 0.001, respectively)." (PMID 18475478, 1992). "In the context of sarcoidosis, granulomatous inflammation is characterized by the dominant expression of the critical cytokines, GM-CSF, IL-1β and T helper 1 (Th1) cytokines, including IFN-γ and TNF-α." (PMID 41476976, 2025). "The levels of TNF-α were significantly higher in non-allergic asthma patients than in sarcoidosis (p = 0.001) and EGPA (p = 0.02) patients." (PMID 40725075, 2025). "Consistently, monocytes in sarcoidosis patients and, to a lesser extent in active TU, exhibited significantly increased enrichment of genes related to the ‘Inflammatory Response’, including IL1B, CXCL8 and TNF." (PMID 40469525, 2025). "Patients being actively treated with methotrexate, TNF inhibitors, or hydroxychloroquine had approximately 4-fold less circulating ILC1s compared with no-treatment sarcoidosis patients." (PMID 39225100, 2024). "Infliximab, a chimeric mouse‐human monoclonal antibody targeting TNF‐α, has shown some effectiveness in treating sarcoidosis, although the available studies have not provided strong evidence to support a high degree of confidence in its efficacy." (PMID 38087813, 2024). "Several theories exist as to why etanercept causes intraocular inflammation, contrary to its TNF α counterparts, it does not inhibit interferon gamma (IFN-γ) which has been shown to cause intraocular inflammation, scleritis, and a sarcoidosis-like syndrome." (PMID 37589912, 2023). "Adler studied effects of TNF inhibitors on sarcoidosis, but there were no patients with musculoskeletal manifestations." (PMID 35943526, 2022). "It is also worth mentioning that drug-related sarcoidosis or sarcoidosis-like reactions have been reported in patients treated with immune-modulators, both PD1 inhibitors used in cancer treatment and anti-TNF or anti-IL6 drugs used in the treatment of CTDs and other systemic autoimmune diseases." (PMID 35441568, 2022).
sarcoidosis (continued). "In addition, we found that the PAR-2/TNF-α and PAR-2/TGF-β ratios can distinguish HP from sarcoidosis." (PMID 33924683, 2021). "In Bechet’s Disease and sarcoidosis, anti-TNFα were used more frequently, and in NMO and SLE, non-anti-TNFα agents were the most frequently prescribed." (PMID 32796717, 2020). "In our cytokine ELISA assays of co-culture medium, two sarcoidosis subjects did not follow the trend of decrease in TNF-α and increase in IL-10 (like all the other patients)." (PMID 31963936, 2020). "In the same way, many cytokines (including IL-1 receptor antagonist, IL-6, IL-8, IFN-γ, and TNF-α) and chemokines (IP-10, MIP-1α, MIP-1β, and RANTES) have been reported to be present in higher concentrations in the vitreous humor of eyes with sarcoidosis than that in those with ERM21,22." (PMID 32066796, 2020). "Despite the lack of high quality evidence, TNF inhibition can currently be considered as standard-of-care in severe cases of refractory sarcoidosis." (PMID 33330556, 2020). "In sarcoidosis, IL-6 responses were significantly higher in subjects with low monocyte CD200R expression when compared with high CD200R expressers, and a similar trend was observed for TNF." (PMID 27929051, 2016). "The role of TNF-blocking agents in treating sarcoidosis is less clear and modulation of one cytokine is unlikely to resolve all aspects of the disease." (PMID 25969669, 2015). "While there are reports on successful treatment of sarcoidosis with UST there is also a case report suggesting a paradoxical sarcoidosis promoting effect under p40 inhibition, similar to what has been reported for TNF blockade." (PMID 27747495, 2015). "It is believed that sarcoidosis is triggered by different mediating infectious agents, following suppression of TNF-alpha cytokine, which plays an important role in the noncalcified granuloma formation seen in sarcoidosis." (PMID 24741443, 2014). "Our aim is to review these off-label uses of anti-TNF blockers in three common conditions: Behçet's disease, sarcoidosis, and noninfectious uveitis." (PMID 23983404, 2013). "Third, we selected only five polymorphisms from TNF-α and TNF-β genes, and did not cover other sarcoidosis-susceptibility genes, such as annexin A11 gene and butyrophilin-like 2 gene." (PMID 24244632, 2013). "In active sarcoidosis, AMs produce high amounts of CCL20, when stimulated by TNF-α and IL-1β." (PMID 24339826, 2013). "TNF-α blockade is an established therapeutic strategy for sarcoidosis, however there are no trials comparing efficacy among the different TNF-α antagonists." (PMID 24276125, 2013). "Currently, FDA-approved therapies for complicated sarcoidosis do not exist and corticosteroids and corticosteroid-sparing immunosuppressive agents (TNFα inhibitors) have met with only limited success." (PMID 22984568, 2012). "Moreover, numerous reports have described the development of the same reactions in patients without a prior history of sarcoidosis following treatment with TNF-α inhibitors, that resolved after the discontinuation of the therapy." (PMID 40647656, 2025). "Sarcoidosis is a chronic granulomatous disorder characterized by unknown etiology, undetermined mechanisms, and non-specific therapies except TNF blockade." (PMID 38250062, 2023). "IL-1β (and not TNFα or IFNy) best reflects granuloma response in this in vitro model and, therefore, may be a useful biomarker for future clinical studies in sarcoidosis." (PMID 37021060, 2023). "Moreover, enhanced TNF-α expression has also been linked to CD14+ monocytes in non-Löfgren and pulmonary monocytes in progressive phenotypes of sarcoidosis." (PMID 36311769, 2022). "The identification of eNAMPT, as a target and biomarker in sarcoidosis is consistent with the top significant dysregulated pathways identified comprised of cytokine-cytokine receptor interaction, MAPK signaling, IL-17, Jak-STAT signaling, chemokine signaling, NF-kappa B, and TNF signaling pathways." (PMID 36388923, 2022).
sarcoidosis (continued). "Although we do not exclude a role for TNF in sarcoidosis, we do implicate these additional cytokines that may need to be inhibited for maximal response to therapy." (PMID 35668129, 2022). "Indeed, targeting TNF-α in sarcoidosis is not a new approach: Infliximab, a readily available anti-TNF-α medication, has been studied in patients with glucocorticoid-refractory disease, with encouraging results." (PMID 34769145, 2021). "Sarcoidosis is a multi-system disease characterized by noncaseating granulomatous inflammation in a Th1/Th17 cytokine environment with elevated levels of IL-2, IL-12, IL-17, TNF- α, and IFN-γ." (PMID 31963936, 2020). "Thus, migration and activation of MAIT cells may contribute to the pathogenesis of sarcoidosis in the lungs through the production of cytokines such as IFN-γ and TNF-α." (PMID 31515495, 2019). "However, this phenomenon is not exclusively for sarcoidosis since also in skin acne an increase of TNF-α after P. acnes stimulation was reported." (PMID 26204953, 2015). "This drug may be considered in refractory sarcoidosis after other TNF-α inhibitors failure, having the advantage of not being associated with neutralizing antibodies development." (PMID 25494723, 2014). "However, there are biological arguments to support imputability of TNFα blockers to sarcoidosis onset as a “class effect” rather than a drug specific phenomen regarding sarcoid-like granulomatous disease occurring during all three anti-TNF therapies." (PMID 24373564, 2013). "COPD patients expressing the highest baseline CRP or TNF-alpha levels also did not demonstrate a significant impact of infliximab on changes from baseline in clinical and biomarker measurements, unlike results recently reported for sarcoidosis." (PMID 22300528, 2012). "The inflammatory response in sarcoidosis is characterized by the increased production of several inflammatory cytokines produced by type 1 helper T (Th1) cells and macrophages, such as interleukin-2 (IL-2), interferon-gamma (IFN-γ), and tumor necrosis factor alpha (TNF-α)." (PMID 22393278, 2012). "Infliximab, a chimeric anti-TNF-α monoclonal antibody, was well tolerated and effectively improved index organ involvement without disease recurrence in a case study of refractory sarcoidosis (nine cases of patients who failed to improve despite moderate-to-high prednisone doses)." (PMID 22195005, 2011). "In addition, biological agents, including anti-TNF-α monoclonal antibodies (infliximab) and anti-CD20 monoclonal antibodies (rituximab) have shown promising therapeutic potential in select group of patients, especially in those with severe or refractory sarcoidosis." (PMID 31182092, 2019). "Interestingly, some TNFα-blocker-induced sarcoidosis patients did not relapse after rechallenging." (PMID 24373564, 2013). "Importantly, TNFα is an essential target for treatment and we found that mo-DCs from patients with sarcoidosis, not influenced by the micro-environment of the lung, induced increased TNFα release upon interaction with naïve CD4+ T cells when compared to controls." (PMID 22513006, 2012). "In African-Americans, quantitative TNF-α levels were higher in sarcoidosis with neurologic disease compared to patients lacking this manifestation (P = 0.022) and to African-American controls (P = 0.0030), with the same patterns maintained when the few patients on TNF-α inhibitors were removed." (PMID 22195005, 2011). "GSEA identified enriched ‘TNF alpha signalling via NF‐κB’ and ‘Inflammatory response’ signatures in CD4+ T cells from sarcoidosis, but not active TU patients, compared to healthy donors." (PMID 40469525, 2025). "A much larger study of 102 sarcoidosis patients showed progressively increased levels of CCL-18 and CCL-17 (a CD4 T-cell chemoattractant), but not TNF-α, in BAL of Scadding stage 1–4 patients (n=32/35/23/12, respectively)." (PMID 36543347, 2022). "TNF-α may be detectable in EBC, however the concentrations were not elevated in sarcoidosis." (PMID 20420721, 2010).
acute respiratory distress syndrome (249 papers, 2005 to 2026). Progressive and life-threatening pulmonary distress in the absence of an underlying pulmonary condition, usually following major trauma or surgery. "This cascade culminates in a CS characterized by excessive IL-6, IL-1β, TNF-α, and IFNs, amplifying lung inflammation and increasing susceptibility to acute respiratory distress syndrome (ARDS)​." (PMID 40330025, 2025). "In particular, IL-6 and TNF-α are the two key cytokines involved in the development of the cytokine storm underlying acute respiratory distress syndrome (ARDS), which can be down-regulated by VD." (PMID 36615826, 2022). "The previous literature concerning both acute lung injury and acute respiratory distress syndrome feature higher local and systemic levels of TNF-α and have been associated with worse outcomes." (PMID 33426360, 2020). "Several reports confirmed that high levels of IL-6 and TNF-α are associated with acute respiratory distress syndrome and acute lung injury." (PMID 25337912, 2014). "Specifically, excess release of TNF-α plays a critical role in disrupting the lung endothelial and epithelial barriers, which may cause acute respiratory distress syndrome (ARDS)." (PMID 33566210, 2021). "Elevated levels of pro-inflammatory cytokines and chemokines (e.g., TNFα, IFNγ, IL-1, IL-6, IL-8, IL-9, IL-12 IL-15, and IL-17) have been found, up to 10 days after the onset of symptoms, in the plasma of patients with acute respiratory distress syndrome (ARDS) caused by influenza A/H1N1." (PMID 32219005, 2019). "Elevated levels of pro-inflammatory cytokines and chemokines (e.g., TNFα, IFNγ, IL-1, IL-6, IL-8, IL-9, IL-12 IL-15, and IL-17) have been found, up to ten days after the onset of symptoms, in the plasma of patients with acute respiratory distress syndrome (ARDS) caused by influenza A/H1N1." (PMID 23148654, 2012). "Specifically, higher levels of IL-1β, IL-6, IL-8, IL-10, IL-18, and TNFα have been found in patients with severe disease and complications, such as acute respiratory distress syndrome (ARDS), which are the main cause of mortality in COVID-19." (PMID 40788382, 2025). "In the context of infectious diseases like COVID-19, vitamin K inhibits pro-inflammatory cytokines (IL-6, IL-1β, and TNF-α) and enhances the integrity of alveolar-capillary membranes reducing the risk of acute respiratory distress syndrome (ARDS)." (PMID 40718363, 2025). "High levels of IL-1β, IL-6, IP-10, and TNFα have been associated with acute respiratory distress syndrome (ARDS), severe disease, and mortality following SARS-CoV-2 infection." (PMID 36865568, 2022). "In severe cases the disease progresses into an Acute Respiratory Distress Syndrome (ARDS), which in turn depends on an overproduction of cytokines (IL-6, TNFα, IL-12, IL-8, CCL-2 and IL1) that causes alveolar and vascular lung damage." (PMID 32922210, 2020). "The overexpression of cytokines such as IL-2, IL-6, IL-7, GSCF, IP10, MCP1, MIP1A, and TNFα is followed by edema, which impairs oxygen exchange, and may lead to acute respiratory distress syndrome (ARDS) causing potential acute cardiac injury, secondary infection, and death." (PMID 32574317, 2020). "Persistent elevation of cytokine concentrations in patient plasma, including TNF-α and IL-1β, is associated with poor prognosis in septic patients with acute respiratory distress syndrome (ARDS)." (PMID 31998291, 2019). "Tumor necrosis factor-α (TNF) is strongly implicated in the development of acute respiratory distress syndrome (ARDS), but its potential as a therapeutic target has been hampered by its complex biology." (PMID 28243236, 2017). "The viral entry initiates a cascade of events that includes the infiltration of proinflammatory markers, such as interleukin-2, interleukin-6, and tumor necrosis factor-alpha, leading to the development of acute respiratory distress syndrome." (PMID 40621321, 2025).